PKP1 (plakophilin 1)
Diseases named in the same sentence as PKP1 in open-access papers (continued):
Sharing a sentence is not in itself a finding about the gene and the disease.
gastric cancer (1 paper, 2011). A primary or metastatic malignant neoplasm involving the stomach. "In gastric cancer, PKP1 expression was unchanged but PKP2 and PKP3 were significantly decreased as compared to normal controls." (PMID 21194493, 2011). "We explored the relationship between plakophilins (PKP1, PKP2, PKP3) to gastric cancer via immunohistochemical techniques." (PMID 21194493, 2011). "In our study, we examined PKP1, PKP2, and PKP3 expression and their clinicopathological correlation with gastric cancer." (PMID 21194493, 2011). "We observed cytoplasmic staining for PKP1, PKP2, and PKP3 in gastric carcinoma." (PMID 21194493, 2011).
Netherton syndrome (1 paper, 2020). Netherton syndrome (NS) is a skin disorder characterized by congenital ichthyosiform erythroderma (CIE), a distinctive hair shaft defect (trichorrhexis invaginata; TI) and atopic manifestations. "PKP1 interacts with desmosomal proteins and regulates desmosomal turnover and signaling, and the interaction between DSG1 and SPINK5 is evidenced by increased DSG1 degradation in mice deficient in SPINK5 as a model of Netherton syndrome, a skin disorder." (PMID 32735560, 2020).
oral squamous cell carcinoma (1 paper, 2018). "Decreased expression of PKP1 in oral squamous cell carcinoma cells increased cell motility, and is associated with the metastatic phenotype of several human cancers." (PMID 30566430, 2018).
oropharyngeal cancer (1 paper, 2025). Carcinoma, predominantly squamous cell, arising from the epithelial cells of the oropharynx. "PKP1 expression is inversely correlated with the histological grade, recurrence and metastasis in patients with oropharyngeal cancer." (PMID 40836964, 2025).
ovarian carcinoma (1 paper, 2020). A malignant neoplasm originating from the surface ovarian epithelium. "To determine the role of PKP1/2/3 in tumorigenesis and development in ovarian cancer, we detected the levels of PKP1/2/3 mRNA in ovarian cancer tissues and normal tissue by Oncomine database." (PMID 33088217, 2020). "We further verified the expression of PKP1/2/3 protein in ovarian cancer tissues and normal tissues by immunohistochemistry with The Human Protein Atlas database." (PMID 33088217, 2020). "In order to further clarify copy number variation of PKP1/2/3 in ovarian cancer, cBioPortal database was adopted to calculate the percentages of gene variation of PKP1/2/3 in ovarian cancer." (PMID 33088217, 2020). "The expression level and prognosis of PKP1 showed little significance in ovarian cancer, and the expression of PKP2/3 mRNA and protein were upregulated in OC, showing significant correlations with poor prognosis of OC." (PMID 33088217, 2020). "Therefore, it is meaningful to investigate potential role and molecular mechanisms of PKP1/2/3 in the development and progression of ovarian cancer." (PMID 33088217, 2020). "However, the expression and molecular mechanisms of PKP1/2/3 in ovarian cancer remain undefined." (PMID 33088217, 2020). "However, the function and potential mechanism of PKP1/2/3 in ovarian cancer (OC) remains unclear." (PMID 33088217, 2020). "However, the expression, prognostic value, biological function and molecular mechanism of PKP1/2/3 in ovarian cancer are not clearly clarified." (PMID 33088217, 2020).
ovarian serous cystadenocarcinoma (1 paper, 2020). A malignant serous cystic epithelial neoplasm arising from the ovary. "We further investigated the expression of PKP1/2/3 in Ovarian serous cystadenocarcinoma (OV) and normal ovarian tissue with the GEPIA database." (PMID 33088217, 2020).
tumor (24 papers, 2011 to 2025). "Conversely, the loss of PKP1 or its cytoplasmic localization is indicative of tumor dedifferentiation, increased invasiveness, and poorer patient outcomes." (PMID 41458151, 2025). "Functionally, the loss of PKP1 contributes to the creation of a pro-oncogenic microenvironment, supporting its role as a tumor suppressor." (PMID 41458151, 2025). "This highlights the critical importance of cellular context and tumor type in the immunological effects of PKP1, ranging from pro-inflammatory (in PCad loss) to immunosuppressive (in NPC gain)." (PMID 41458151, 2025). "In this work, we have unambiguously demonstrated a direct association between RYBP and PKP1, two proteins separately known to be involved in several types of tumor processes." (PMID 38785968, 2024). "As a result, PKP1, a potential molecular biomarker associated with immune infiltration, and tumor-infiltrating lymphocyte-B cells (TIL-Bs) were identified as promising therapeutic targets for NPC." (PMID 36186467, 2022). "In PCad, a deficiency in PKP1 is characteristic of aggressive phenotypes and is directly linked to a significant increase in the infiltration of diverse immune cells, including T cells, B cells, macrophages, and neutrophils, into tumor areas." (PMID 41458151, 2025). "Epigenetic reactivation: Demethylating agents (decitabine, 5-aza-dC) to restore PKP1’s tumor-suppressive functions." (PMID 41458151, 2025). "As detailed in preceding sections, PKP1 expression and subcellular localization exhibit remarkable heterogeneity in neoplastic tissues, correlating with tumor type, differentiation status, recurrence, metastasis, and invasive potential." (PMID 41458151, 2025). "The context-dependent duality of PKP1—acting as either a tumor suppressor or an oncoprotein—raises a fundamental question in cancer biology: what molecular mechanisms govern these opposing functions?" (PMID 41458151, 2025). "This is particularly intriguing given that PKP1 is primarily known as a desmosomal component involved in cell adhesion, typically regarded as a tumor suppressor." (PMID 40890861, 2025). "The functional roles of PKP1 in tumor suppression versus progression are critically influenced by its subcellular localization, phosphorylation status, and protein interactions." (PMID 41458151, 2025). "PKP1 expression is subject to dynamic regulation during oncogenesis and tumor progression, exhibiting strong correlations with tumor differentiation, aggressiveness, and metastatic potential." (PMID 41458151, 2025). "In human malignancies, PKP1 demonstrates a context-dependent functional dichotomy, challenging the traditional classification of oncogenes and tumor suppressors." (PMID 41458151, 2025). "These context-dependent patterns position PKP1 as a promising biomarker with multifaceted clinical utility in tumor differentiation, staging, and prognosis prediction." (PMID 41458151, 2025). "This review employs a multi-tiered approach to address existing knowledge gaps: firstly, it systematically compares the oncogenic and tumor-suppressive roles of PKP1 across various cancer types to elucidate tissue-specific mechanisms." (PMID 41458151, 2025). "In essence, PKP1 functions as a molecular switch at the intersection of tumor cell signaling and immune communication." (PMID 41458151, 2025). "Accumulating evidence suggests that PKP1 functions as a tumor suppressor in various cancer contexts." (PMID 41458151, 2025). "The prevailing model suggests a spatial functional switch: Membrane-bound PKP1 maintains epithelial integrity by stabilizing desmosomal adhesion, thereby exerting a tumor-suppressive role." (PMID 41458151, 2025). "In the context of the current knowledge of the biological pathways both proteins participate in, we propose a possible novel role for RYBP as a rescuer in some tumor cells with a high content of PKP1." (PMID 38785968, 2024).
tumor (continued). "Several mechanisms have been described that mediate RIPK4’s tumor suppression such as the phosphorylation of PKP1 and STAT3." (PMID 36765696, 2023). "It is possible that TIL-B cells produce immunoglobulin G (IgG) to tumor antigens, such as PKP1, or viral antigens, including EBV and HPV, to execute antitumor ability through DC and T cells." (PMID 36186467, 2022). "In NSCLC, desmosomal proteins plakophilin 1 and DSC1 were previously verified to be associated with tumor development and prognosis." (PMID 36193204, 2022). "Subsequently, we also described the localization of PKP1 in nucleus, cytoplasm, and cell membrane in tumours and proposed the utilization of these proteins as immunohistochemical markers." (PMID 31809668, 2020). "These methodologies can definitively ascertain whether the immunomodulatory functions of PKP1 are inherent to the tumor cell or necessitate its activity within immune populations." (PMID 41458151, 2025). "Collectively, these findings highlight PKP1 as a crucial modulator in tumor biology." (PMID 41458151, 2025). "This spatial and functional segregation, further refined by phosphorylation, ultimately dictates whether PKP1 constrains or promotes tumor progression." (PMID 41458151, 2025). "In NPC, PKP1-positive tumor cells exert immunosuppressive effects through a distinct mechanism." (PMID 41458151, 2025). "However, phosphorylation at Ser143 by RIPK4, located within the N-terminal domain of PKP1, promotes epidermal differentiation and maintains its tumor-suppressive function, underscoring the delicate balance regulated by kinase activities." (PMID 41458151, 2025). "Our findings could be of importance to understand how cancer development or even the EMT mechanism can be regulated in the cell; in fact, we hypothesize that RYBP could act as a rescuer in the presence of a large amount of PKP1 in some types of tumor cells." (PMID 38785968, 2024). "The analysis revealed a significant association between elevated PKP1 expression and various clinicopathological characteristics of ESCC, including tumor size (p = 0.0267), invasion depth (p = 0.0016), lymph node metastasis (p = 0.0251), and clinical stage (p = 0.0102)." (PMID 38515846, 2024). "We further explored the relationship between PKP1/2/3 mRNA and tumor stages in OV." (PMID 33088217, 2020). "The results suggested that the level of PKP2 mRNA was associated with the tumor stages (P < 0.05), while the levels of PKP1 and PKP3 mRNA were not significantly different among the tumor stages (P > 0.05)." (PMID 33088217, 2020). "Based on the function of PKP1 in protein translation, researchers found that PKP1 could regulate cell growth and proliferation, thus affecting tumor progression and invasion." (PMID 33088217, 2020). "Similar to PKP1, CTNNA1, catenin cadherin-associated protein, alpha 1 (GeneBank: 1495) and AJAP1, adherens junctions associated protein 1 (GeneBank: 55966) expression levels are correlated with advancing tumor stage and inversely related to cell proliferation." (PMID 29052507, 2017). "Furthermore, nanocarrier-based delivery systems could improve the tumor-specific bioavailability of PKP1-targeted agents." (PMID 41458151, 2025). "In OSCC, the reduced expression of PKP1 caused a marked redistribution of DSP from the cell borders to diffuse cytoplasmic localization, resulting in decreased desmosome assembly and altered cell-cell adhesion, thereby increasing tumor cell motility and invasion." (PMID 34203070, 2021). "In addition, PKP3 could closely bind to RNA-binding proteins such as FXR1 and PABPC1, indicating that PKP1/2/3 can participate in cell connection and tumor progression through its interacting proteins." (PMID 33088217, 2020). "Thus, we suppose that down-regulation of PKP1 induced by P. gingivalis may enhance cell metastasis during tumor development." (PMID 28286742, 2017).
tumor (continued). "This could be accomplished by leveraging synthetic lethality interactions specific to PKP1-overexpressing cancer cells or by developing approaches that selectively degrade the oncogenic cytoplasmic/nuclear pools of PKP1 without disrupting its tumor-suppressive membrane-associated functions." (PMID 41458151, 2025). "Plakophilin 1 (PKP1) is a desmosomal protein that plays a dual role in cancer, acting as either an oncogene or a tumor suppressor depending on the context." (PMID 41458151, 2025). "Tumor-hypoxia-related studies that are directly relevant to B4GALNT2 and PKP1 in hypoxia are few and far between." (PMID 35757722, 2022). "Immunohistochemical staining for PKP1 was mainly detected in SCC, with a heterogeneous distribution and intensity among the different tumours analyzed, and in different areas of the same neoplasm." (PMID 31809668, 2020). "Concomitantly α2β1 down regulated the expression of two other tumor suppressors, namely PKP1 (plakophilin 1) and CDH5 (chromodomain helicase DNA binding protein 5)." (PMID 30197754, 2018). "PKP1 promotes cancer cell survival and metastasis via cluster formation in the circulatory system and, as it happens with RYBP, it has been reported to be both an oncogene and a tumor suppressor." (PMID 38785968, 2024). "TMEM108 and C3orf47 were positively correlated with tumor grade and eight genes, including LAD1, TIF1, FGF11, carbonic anhydrase 12 (CA12), G protein subunit α15 (GNA15), junction plakoglobin (JUP), plakophilin 1 (PKP1) and PPARD, were negatively correlated with the tumor grade of ESCC patients." (PMID 28904855, 2017). "There was no observable clinical association with PKP1 or PKP2 expression; however, low PKP3 level and poor prognosis appeared to correlate with regards to node number and tumor stage." (PMID 21194493, 2011). "Thus, on the basis of our results describing the binding between the two proteins, we could also hypothesize that the interaction between RYBP and PKP1 could act as a rescuer of the excess of PKP1, decreasing the amount of EMT in tumor cells." (PMID 38785968, 2024). "Therefore, PKP1 and PKP3 play a tumor suppressor role in HNC." (PMID 34203070, 2021). "Since PKP1 and RYBP (i) are involved in the development of several types of cancers, (ii) can both be oncogenes and tumor suppressors, and (iii) mutually interact with the citrullinating enzyme PADI4, we hypothesized that RYBP could also be capable of binding to ARM-PKP1." (PMID 38785968, 2024). "Interestingly, PKP1 is reported to be a tumor suppressor but not yet been described in NPC." (PMID 34648530, 2021).
cancer (10 papers, 2018 to 2025). A tumor composed of atypical neoplastic, often pleomorphic cells that invade other tissues. "Concurrently, epigenetic silencing via promoter methylation represents a key mechanism underlying PKP1 dysregulation in cancer." (PMID 41458151, 2025). "Across various cancer types (e.g., cutaneous and oropharyngeal SCCs, BCCs), a consistent prognostic pattern is observed: the retention of membranous PKP1 is associated with well-differentiated histology and a reduced risk of metastasis." (PMID 41458151, 2025). "In prostate adenocarcinoma (PCad), the downregulation of PKP1 in aggressive phenotypes is associated with enhanced proinflammatory cytokine stability, thereby fostering an immunosuppressive microenvironment that accelerates cancer progression." (PMID 41458151, 2025). "The pathological role of plakophilin (PKP1) is associated mainly with dysplasia and cancer." (PMID 40836964, 2025). "PKP1 is associated with mRNA ribonucleoprotein particles and ribosomal proteins, and its altered expression is a frequent and critical event in the progression of several cancers, indicating that it has key roles in cell proliferation, differentiation, and migration." (PMID 38785968, 2024). "The evolving landscape of cancer diagnostics is increasingly emphasizing the integration of artificial intelligence-assisted and digital pathology platforms, where the role of PKP1 is anticipated to expand." (PMID 41458151, 2025). "This spatial segregation of functions within the same cancer type highlights PKP1’s complex regulatory landscape." (PMID 41458151, 2025). "This emerging paradigm challenges a singular explanation and instead advocates for a nuanced, context-defined understanding of PKP1’s role in cancer immunology." (PMID 41458151, 2025). "Analyses utilizing the OncomineTM platform reveal significant dysregulation of PKP1 across a range of malignancies, with particularly notable alterations in certain cancer types." (PMID 41458151, 2025). "The high expression of PKP1 facilitated cancer cells to form clusters in circulation and also activated the PI3K/AKT/Bcl–2–mediated pathway to increase cell survival." (PMID 38595789, 2024). "Clinically, PKP1 expression is valuable for cancer subtyping and prognosis." (PMID 41458151, 2025). "PKP1 also plays a direct role in reprogramming cancer cell metabolism." (PMID 41458151, 2025). "Context-dependent roles of PKP1 across different cancer types." (PMID 41458151, 2025). "In conclusion, the biological functions of PKP1 are significantly influenced by a dynamic interplay between its subcellular localization and specific protein interactions, which underpin its context-dependent dualism in cancer." (PMID 41458151, 2025). "Our findings suggest that RYBP might be a rescuer of the high expression of PKP1 in tumors, where it could decrease the epithelial–mesenchymal transition in some cancer cells." (PMID 38785968, 2024). "Therefore, it is necessary to further understand the mechanisms by which PKP1 and PKP3 are downregulated and how their loss promotes cancer progression." (PMID 34203070, 2021). "In recent years, the role of PKPs in the invasion and metastasis of malignant tumors has gradually attracted the attention of many experts, and the function of PKP1/2/3 has been preliminarily validated in the occurrence and development of many malignant tumors." (PMID 33088217, 2020). "The reciprocal regulation between Ca2+ and Wnt signaling creates a PKP1-mediated switch that toggles between “adhesion maintenance” (high Ca2+) and “proliferation/migration” (Wnt activation), with significant implications for cancer metastasis and tissue homeostasis." (PMID 41458151, 2025). "The expression of different catenin molecules in different cancer tissues was inconsistent, and several molecules, including PKP3, PKP2, PKP1, and JUP, were overexpressed in several cancer tissues." (PMID 37924160, 2023).
cancer (continued). "Previous studies confirmed that PKP1 and PKP3 levels are elevated in several cancer tissues compared to normal tissues and regulate the proliferation and invasive capacity of cancer cells." (PMID 37924160, 2023). "The functional duality of PKP1 is mediated through its integration into critical oncogenic signaling pathways, including Wnt/β-catenin, Ca2+, PI3K/AKT, and MAPK, which collectively influence cell fate decisions in cancer." (PMID 41458151, 2025). "PKP1, as a HPR gene, has been documented to exhibit aberrant expression in various cancers." (PMID 38515846, 2024). "Based on these data, we hypothesized that PKP1 and RYBP could interact directly with each other, at least in some of those cancer cell lines." (PMID 38785968, 2024). "To test whether interaction between endogenous intact PKP1 and RYBP occurred within cells, we used cancer and non-cancer cell lines." (PMID 38785968, 2024).
adenocarcinoma (2 papers, 2011 to 2025). A common cancer characterized by the presence of malignant glandular cells. "By incorporating PKP1 into algorithm-driven panels that integrate IHC, genomic, and morphologic features (e.g., alongside PD-L1 for immune context, TTF-1/Napsin A for adenocarcinoma, and p63 for SCC), its contribution can be dynamically weighted to enhance diagnostic accuracy." (PMID 41458151, 2025).
lung (1 paper, 2020). "Materials and methods: We compared the usefulness of six conventional (CK5/6, p40, p63, CK7, TTF1, and Napsin A) and three novel (PKP1, KRT15, and DSG3) markers to distinguish between lung SCC and AC in 85 small biopsy specimens (41 ACs and 44 SCCs)." (PMID 31809668, 2020).